LOXL1 (lysyl oxidase like 1)
Diseases named in the same sentence as LOXL1 in open-access papers (continued):
Sharing a sentence is not in itself a finding about the gene and the disease.
cancer (continued). "Kaplan–Meier analysis was then performed and the results demonstrated that high LOXL1 expression predicted shorter OS and DFS in a variety of cancer types." (PMID 38267662, 2024). "We found that LOXL1 and LOXL4 remarkably enhanced cancer invasiveness among the LOX family genes with altered expression." (PMID 36910659, 2023). "Also, key subtype differences in immunomodulatory and matrix-modifying protein release identified in our previous experiments could be captured in serum, such as high Loxl1 and Csf1 secretion by mesenchymal cancer cells, providing direct evidence for potential long-range effects." (PMID 37156840, 2023). "We further identified multiple cancer-relevant target genes of the Zn2+-activated ZEB1, among which LOXL1 and LOXL2, in particular, function as pioneer factors for invasiveness." (PMID 36910659, 2023). "LOX family members (LOX, LOXL1, LOXL2, LOXL3, LOXL4) reportedly mediate cell migration and metastasis of different cancers." (PMID 34815382, 2021). "Cancer induced changes in the activity of these processing proteinases likely has a knock-on effect on LOX and LOXL1 collagen cross-linking activity." (PMID 33513979, 2021). "LOX, LOXL1, and LOXL2 were upregulated in certain kinds of cancers, and only LOX and LOXL2 were significantly elevated in RCC." (PMID 32970930, 2020). "The LOXL1 protein plays a key role in the maturation of elastin and the remodeling of the extracellular matrix (ECM) during tissue injury, fibrotic diseases, and the progression of malignant tumors." (PMID 40786111, 2025). "This study aimed to identify effective biomarkers predictive of prognosis and efficacy of immunotherapy in CRC patients, and to elucidate the prognostic value, clinical relevance, functional and molecular features, and immunotherapy predictive role of LOXL1 in CRC and pan-cancer." (PMID 38267662, 2024). "LOXL1 could also stabilize the molecular chaperone regulator BAG2 and impede the apoptosis of cancer cells." (PMID 38267662, 2024). "Moreover, the lysyl oxidase (LOX) family members LOX, LOXL1, and LOXL4 have attracted much attention due to their critical role in cancer metastasis." (PMID 36910659, 2023). "Additionally, POSTN and lysyl oxidase-like 1 (LOXL1) overexpressed by CAFs degrade the basement membrane and stromal ECM and initiate the invasion of malignant tumors." (PMID 37234990, 2023). "Moreover, the structural homolog of LOXL1, LOX, transcriptionally regulates SNAI2 expression by transactivating the SNAI2 promoter in human cancer cells." (PMID 33095806, 2020). "Similarly, the expression of the four MPM biomarker candidates LOX, LOXL1, LOXL2 and ZFPM2 were shown to be significantly increased in the MPM tissues when compared to the non-cancer patient samples." (PMID 31921422, 2020). "Besides, WTAP regulates the expression of certain genes related to motility of cancer cells, such as chemokine ligand 2 (CCL2), chemokine ligand 3 (CCL3), matrix metallopeptidase 3 (MMP3), lysyl oxidase-like 1 (LOXL1), hyaluronan synthase 1 (HAS1), and thrombospondin 1 (THBS1)." (PMID 30062093, 2018).
CNS tumor (1 paper, 2024). "According to the new 2021 WHO CNS tumor classification for GBM, we excluded IDH1-mutant patients from three GBM cohorts and further assessed the Loxl1-based model in IDH1-WT GBM cohorts." (PMID 38978755, 2024).
connective tissue disease (1 paper, 2025). "The finding of thin corneas in Loxl1−/− mice revealed in this study is in line with ocular findings of connective tissue disease overall." (PMID 41009782, 2025).
heart disease (1 paper, 2019). "Less information is available about LOXL1 and cardiac diseases." (PMID 31766500, 2019).
inflammation (1 paper, 2024). Aberrant reaction of the microcirculation characterized by movement of fluid and leukocytes from the blood into extravascular tissues. "Finally, we tried to explore the possible mechanisms of LOXL1 involvement in the development of RA synovial inflammation." (PMID 38217541, 2024).
neurodegenerative disease (1 paper, 2023). A disorder of the central nervous system characterized by gradual and progressive loss of neural tissue and neurologic function. "One hypothesis is that LOXL1 protein for aggregates and is actively cleared by autophagy in cells from patients with shedding syndrome (XFG), a cellular defect also found in neurodegenerative diseases such as AD and PD." (PMID 36825022, 2023).
LOXL1 also shares sentences with these, for which no sentence is quoted: primary open-angle glaucoma (14 papers); pigmentary glaucoma (4); breast tumour (3); primary angle-closure glaucoma (3); prostate carcinoma (3); cardiovascular disease (2); malignant glioma (2); abdominal aortic aneurysm (1); Alzheimer disease (1); aortic aneurysm (1); atrial fibrillation (1); brain glioma (1); breast adenocarcinoma (1); carotid atherosclerosis (1); cerebrovascular disease (1); chronic obstructive pulmonary disease (1); colon cancer (1); diabetes mellitus (1); diabetic retinopathy (1); dilated cardiomyopathy (1); fibrosis (1); heart failure (1); hepatocellular carcinoma (1); Hypertension (1); hypertrophic cardiomyopathy (1); hypertrophy (1); invasive lobular carcinoma (1); joint diseases (1); kidney carcinoma (1); leukoplakia (1).
A further 20 diseases each share a sentence with LOXL1 in 1 paper.